CHST4 (carbohydrate sulfotransferase 4)
Diseases named in the same sentence as CHST4 in open-access papers (continued):
Sharing a sentence is not in itself a finding about the gene and the disease.
tumor (8 papers, 2015 to 2025). "CHST4 also takes part in tumor by implicated in the ectopic expression of MECA-79, which is a newfangled diagnosis signal." (PMID 35294478, 2022). "In keeping with the phenotypic loss of HEVs in tumor LNs, the expression levels of Glycam1, Chst4, Icam1, and Ccl21a were progressively reduced in HEC1 to HEC3, similar to the reduction of gene expression of PNAd producing glycan-generating enzymes." (PMID 34706240, 2021). "As low CHST4 expression in HBV-HCC tumor tissues was associated with malignant clinicopathological features, we explored the biological function of CHST4 in HCC cells." (PMID 33178582, 2020). "Overall, our findings suggest that CHST4 acts as a tumor suppressor in HCC-HBV and represents a potential diagnostic and therapeutic target." (PMID 33178582, 2020). "CHST4 expression is associated with improved prognosis, potentially influencing tumor immunity." (PMID 40362535, 2025). "To conclude, results of their analysis suggest that CHST4 expression could be recognised as a tumour suppressor in HBV positive HCC and potential diagnostic and therapeutic target." (PMID 37545696, 2023). "Based on gene expression profiles, the gene expression difference of CHST4 between tumor and normal samples was the most significant." (PMID 35294478, 2022). "Our previous observation of PNAd expression on both surfaces of tumor endothelium is consistent with the very low level of Chst4 expression in TEC, and suggests that Chst2 is largely responsible for synthesizing 6-sulfo-sialyl Lewis X in TEC." (PMID 36189308, 2022). "Quantitative PCR (qPCR) demonstrated that CHST4 was significantly overexpressed in tumor tissues, verifying the role of CHST4 as the core gene of CCA." (PMID 35294478, 2022). "CHST4 expression was significantly lower in HBV-HCC tumor tissues than the corresponding normal tissue, while only miR-10b-5p was more highly expressed (P < 0.01)." (PMID 33178582, 2020). "We also found significant differences in the expression of CHST4 among different subtypes of the same tumor." (PMID 33178582, 2020). "We found that CHST4 expression was lower in tumor tissues than in normal tissues, and HBV-HCC patients with high CHST4 expression had longer OS and DFS." (PMID 33178582, 2020). "We also found that tumor expression of CHST4 at the mRNA and protein level is only partially consistent." (PMID 33178582, 2020). "Therefore, the relationship between CHST4 expression and prognosis varies according to the tumor type." (PMID 33178582, 2020). "Here we confirm that CHST4 is aberrantly expressed in various tumor subtypes." (PMID 33178582, 2020). "We also used the cBioPortal database to analyze CHST4 gene alterations in 32 human tumor types." (PMID 33178582, 2020). "Therefore, overall findings indicate that CHST4 can recruit immune cells into the tumor microenvironment in HBV-HCC." (PMID 33178582, 2020). "It is hypothesized that CHST4 contributes to tumor immunity against malignant tumors." (PMID 40362535, 2025). "Therefore, we focused on the aberrant expression of CHST4 in tumor tissues." (PMID 33178582, 2020). "Therefore, CHST4 might recruit immune cells with tumor-killing activity into the tumor microenvironment, thus inhibiting the occurrence and development of HBV-HCC." (PMID 33178582, 2020). "Therefore, we speculate that CHST4 may be a potential biomarker for specific tumor subtypes, and this hypothesis should be validated in future studies." (PMID 33178582, 2020). "However, the specific functions and roles of CHST4 in tumor progression are largely unknown." (PMID 33178582, 2020). "We further illuminated the anti-tumor role and mechanism of CHST4 in HBV-HCC by constructing a FENDRR–miR-10b-5p–CHST4 competing endogenous RNA network." (PMID 33178582, 2020). "In HCC, patients with high CHST4 expression had shorter OS and DFS, which suggests that CHST4 plays a tumor-promoting role in HCC." (PMID 33178582, 2020).
tumor (continued). "In particular, we showed that CHST4 inhibits HCC progression, likely through recruiting immune cells to the tumor microenvironment." (PMID 33178582, 2020). "Using this approach, 7 genes were identified as undergoing tumor-specific aberrant promoter methylation in HCC, including IFITM1, SMAD6, TBX15, CHST4, and LRRC4 with hyper-methylated promoters and CCL20 and NQO1 with hypo-methylated promoters." (PMID 26300991, 2015). "Their results also indicate a possible role of CHST4 in CD4+ T cells, macrophages, dendritic cells and neutrophils recruitment into tumour microenvironment which may lead to inhibition of tumour progression." (PMID 37545696, 2023). "We compared the expression levels of CHST4 and differentially expressed miRNAs and lncRNAs between normal and tumor tissues in human HBV-HCC from TCGA." (PMID 33178582, 2020). "Additionally, in vitro experiments confirmed that ectopic overexpression of CHST4 inhibited the proliferation and metastasis of HCC, while silencing of CHST4 expression promoted tumor progression." (PMID 33178582, 2020). "CHST4 may also recruit CD4+ T cells, macrophages, dendritic cells, and neutrophils into the tumor microenvironment to inhibit the progression of HBV-HCC." (PMID 33178582, 2020). "However, together with the lower expression levels of multiple glycosyl transferases, particularly Chst4, the overall lower level of Podxl, Glycam1, and Cd300lg in PNAd+ TEC may also contribute to the lower level of PNAd expression on the tumor vasculature." (PMID 36189308, 2022). "CHST4 expression was found to be related to viral gene expression, and thus, low CHST4 expression may promote HBV expression and replication in HCC, thereby increasing chromosomal instability and tumor cell proliferation." (PMID 33178582, 2020). "In addition, immunohistochemistry (IHC) was performed on surgical specimens, but in one case, the CHST4 expression could not be scored because of low tumor-cell counts." (PMID 38396947, 2024). "CHST4, as a prognostic marker and being independent of the conventional TNM classification, can enable a more accurate assessment of tumor malignancy." (PMID 38396947, 2024). "We found that 7 genes (IFITM1, SMAD6, TBX15, CHST4, LRRC4, CCL20, and NQO1) showed significantly different promoter methylation levels between tumor and non-tumor tissue (P value < 0.001) in approximately 80 % of the 78 HCCs." (PMID 26300991, 2015). "However, TBX15, LRRC4, and CHST4 showed no systematic difference in expression between HCC and non-tumor liver cell lines." (PMID 26300991, 2015). "Although CHST4 is not a gene that is specifically expressed in MPM and is limited to cases in which a definitive diagnosis has been obtained via biopsy or other means, CHST4 may be involved in tumor immunity to MPM and can be used to predict therapeutic efficacy and prognosis." (PMID 38396947, 2024).
CHST4 also shares sentences with these, for which no sentence is quoted: rheumatoid arthritis (2 papers); acute lymphoblastic leukaemia (1); gastric cancer (1); glioblastoma (1); infection (1); malignant pleural mesothelioma (1); melanoma (1); mucinous adenocarcinoma (1); neuroblastoma (1); osteoarthritis (1); prostate adenocarcinoma (1); renal clear cell carcinoma (1); skin cutaneous melanoma (1); thyroid papillary carcinoma (1); uterine cancer (1); uveal melanoma (1).